ADGRF1 (adhesion G protein-coupled receptor F1)
Description:
Adhesion G protein-coupled receptor (aGPCR) for N-docosahexaenoylethanolamine (synaptamide), an omega-3 fatty acid lipid highly enriched in the brain. Ligand binding causes a conformation change that triggers signaling via guanine nucleotide-binding proteins (G proteins) and modulates the activity of downstream effectors, such as adenylate cyclase. ADGRF1 is coupled to G(s) G proteins and mediates activation of adenylate cyclase activity. Also able to couple to G(q), G(i) and G(12)/G(13) G proteins; additional evidence is however required to confirm this result in vivo. Involved in the development of neurons and cognitive function (By similarity). In liver, involved in fat accumulation (By similarity).
Synonyms: GPR110; PGR19; hGPCR36; KPG_012
Tractability: Small molecule: a structure with a bound ligand is known. Antibody: UniProt places it where antibodies can reach, with high confidence; its Gene Ontology location is reachable by antibodies, with high confidence; UniProt predicts a signal peptide or a membrane-spanning region. PROTAC: a small molecule that binds it is known.
Target class: Family B G protein-coupled receptor; Membrane receptor
Gene: Protein-coding gene on chromosome 6 (46,997,708 to 47,042,350, reverse strand). Ensembl gene ENSG00000153292.
Subcellular location: Cell membrane; Secreted (Isoform 2)
Gene Ontology:
Molecular function: G protein-coupled receptor activity; protein binding; transmembrane signaling receptor activity
Biological process: adenylate cyclase-activating G protein-coupled receptor signaling pathway; G protein-coupled receptor signaling pathway; neuron projection development; synapse assembly; cell surface receptor signaling pathway
Cellular component: extracellular region; plasma membrane; membrane
Genetic constraint (gnomAD): Loss-of-function variants: 68 observed, 66.75 expected, observed/expected ratio (o/e) 1.02, 90% interval 0.84 to 1.25. The upper end of that interval is the gene's LOEUF score, 1.25, which puts it in group 5 of 6, group 1 being the genes least tolerant of losing a copy. Missense variants: 1,022 observed, 992.81 expected, observed/expected ratio (o/e) 1.03, 90% interval 0.98 to 1.08. Synonymous variants: 390 observed, 385.51 expected, observed/expected ratio (o/e) 1.01, 90% interval 0.93 to 1.1.
Homologues: Orthologues: chimpanzee ADGRF1 (99% identical), macaque ADGRF1 (90% identical), dog ADGRF1 (79% identical), rabbit ADGRF1 (77% identical), pig ADGRF1 (75% identical), mouse Adgrf1 (70% identical), rat Adgrf1 (67% identical), guinea pig ADGRF1 (54% identical), zebrafish adgrf8 (31% identical), zebrafish adgrf6 (28% identical), zebrafish adgrf11 (21% identical), zebrafish adgrf7 (21% identical). Paralogues in human: ADGRF5 (32% identical), ADGRF4 (26% identical), ADGRF3 (22% identical), ADGRL3 (18% identical), ADGRL2 (18% identical), ADGRL1 (17% identical), ADGRB1 (17% identical), ADGRB3 (17% identical), ADGRG4 (17% identical), ADGRB2 (16% identical), ADGRD2 (16% identical), ADGRD1 (15% identical), and 30 more.
Diseases named in the same sentence as ADGRF1 in open-access papers:
ADGRF1 is named in the same sentence as 33 diseases in open-access papers, as found by Europe PMC text mining. Sharing a sentence is not in itself a finding about the gene and the disease. The quoted sentences say what the papers report.
breast carcinoma (7 papers, 2021 to 2024). "The overexpression of ADGRF1 has been reported in breast cancer." (PMID 37935791, 2024). "Additionally, associations have been drawn between ADGRF1 (GPR110) and breast cancer progression, as well as ADGRL3 and attention-deficit/hyperactivity disorder." (PMID 38047990, 2023). "Among top downregulated genes, amphiregulin (AREG) is involved in EMT and growth in different types of cancer, including PDAC, while Adhesion G Protein-Coupled Receptor F1 (ADGRF1) has an important role in inducing quiescence and chemoresistance in breast cancer." (PMID 37174038, 2023). "It has been reported that GPR110 (ADGRF1) can induce cell cycle arrest and chemoresistance in breast cancer." (PMID 34572869, 2021).
Glucose intolerance (1 paper, 2023). Glucose intolerance (GI) can be defined as dysglycemia that comprises both prediabetes and diabetes. "Deletion of hepatic Adgrf1 protects against diet-induced glucose intolerance in Adgrf1 overexpress mice." (PMID 37580962, 2023).
Hepatic steatosis (1 paper, 2023). Steatosis is a term used to denote lipid accumulation within hepatocytes. "We used recombinant adeno-associated virus-mediated gene delivery system, and antisense oligonucleotide was used to manipulate the hepatic Adgrf1 expression level in diet-induced obese mice to investigate the role of Adgrf1 in hepatic steatosis." (PMID 37580962, 2023). "Treatment with the liver-specific Scd1 inhibitor MK8245 and specific shRNAs against Scd1 in primary hepatocytes improved the hepatic steatosis of Adgrf1-overexpressing mice and lipid profile of hepatocytes, respectively." (PMID 37580962, 2023). "Treating mice with high levels of liver fat with molecules that inhibit Scd1 decreased the symptoms of Adgrf1-mediated fatty liver disease." (PMID 37580962, 2023). "Based on the dramatic difference in expression levels of hepatic ADGRF1 before and after HFD treatment, we hypothesized that downregulation of Adgrf1 in HFD-fed mice may be involved in the pathogenesis of fatty liver." (PMID 37580962, 2023).
Insulin resistance (1 paper, 2023). Increased resistance towards insulin, that is, diminished effectiveness of insulin in reducing blood glucose levels. "Overexpressing Adgrf1 in the liver of STC-fed mice did not affect body weight, fasting glucose level, fasting insulin level, and homeostatic model assessment for insulin resistance (HOMA-IR)." (PMID 37580962, 2023).
Obesity (1 paper, 2023). Accumulation of substantial excess body fat. "The argument mainly based on the findings that HFD-induced steatosis and liver injury were exacerbated in obese mice with high Adgrf1 overexpression level, and knockdown hepatic Adgrf1 alleviated the severity of obesity-induced NAFLD." (PMID 37580962, 2023).
steatosis (1 paper, 2023). Increased lipid within the cytoplasm of cells. "Immunostaining analysis demonstrated that hepatic expression of Adgrf1 protein was higher in the ones with severe steatosis than those with lower degree of NAFLD." (PMID 37580962, 2023).
uterine corpus endometrial carcinoma (1 paper, 2025). A endometrial carcinoma (disease) that involves the body of uterus. "Correlation studies of ADGRs reveals that ADGRG3, ADGRA1, ADGRF1, CD4T cells and CD8 cells were involved in the tumor-related inflammatory response of uterine corpus endometrial carcinoma (UCEC) patients, and affected the clinical prognosis of UCEC patients." (PMID 40110435, 2025).
tumor (11 papers, 2010 to 2025). "For instance, ADGRF1 switches from tumor-promoting to tumor-suppressive functions upon interaction with laminin-111, enhancing sensitivity to anti-HER2 drugs in HER2 + BC." (PMID 40781676, 2025). "Interestingly, some of the common down-regulated genes, such as EPHA7 and NSUN7, are known for both their tumor suppressing and promoting roles, or are associated with overall survival (OS) (SLC22A31), while others have clear pro-tumorigenic roles (ADGRF1, LOX, LY6G5C, SNAI2, TNFRSF11B, ZNF233)." (PMID 36769365, 2023).
cancer (8 papers, 2012 to 2024). A tumor composed of atypical neoplastic, often pleomorphic cells that invade other tissues. "The evidence is mainly based on high expression of Adgrf1 in numerous cancer types, and knockdown Adgrf1 can reduce the cell migration, invasion, and proliferation." (PMID 37580962, 2023). "In general, overexpression of Adgrf1 was observed in various cancers, and it was required to promote cancer cell survival, proliferation, and migration." (PMID 37580962, 2023). "Therefore, a further experiment to check the Scd1 expression level in the Adgrf1 induced cancers may be conducted." (PMID 37580962, 2023).
ADGRF1 also shares sentences with these, for which no sentence is quoted: prostate carcinoma (10 papers); injury (2); lung carcinoma (2); T lymphomas (2); acute kidney injury (1); Anxiety (1); attention deficit-hyperactivity disorder (1); benign prostate hyperplasia (1); cardiovascular diseases (1); Coeliac disease (1); colorectal cancer (1); depression (1); gastric cancer (1); glioma (1); hepatocellular carcinoma (1); infection (1); lung adenocarcinoma (1); mood disorder (1); non-alcoholic fatty liver disease (1); pancreatic cancer (1); prostate adenocarcinoma (1); prostate tumor (1); thyroid carcinoma (1); triple-negative breast carcinoma (1).